C5AR1 (complement C5a receptor 1)
Diseases named in the same sentence as C5AR1 in open-access papers (continued):
Sharing a sentence is not in itself a finding about the gene and the disease.
tumor (continued). "Bulk RNA-seq analysis of CD1c+CD14+ cells sorted from tumor-invaded lymph nodes indicated that they displayed a similar expression profile as blood DC3s (high expression of cDC2 markers such as CLEC10A and FCER1A combined with low expression of monocyte-associated markers such as C5AR1 and SOD2)." (PMID 32610077, 2020). "Upon signaling by C5a stimulation, C5aR1 expressed tumor cells underwent cytoskeletal rearrangement (e.g. filopodia formation, membrane ruffling) and furthermore released matrix metalloproteinase, which lead to increased tumor cell motility and invasiveness both in vitro and in vivo." (PMID 33193442, 2020). "Moreover, activation of C5aR1 in tumor cells leads to an increased prometastatic activity." (PMID 31001273, 2019). "In this study, we demonstrate that C3, C3AR1, and C5AR1 are robustly expressed in GBM cells, indicating potential tumor cell-specific functions of these complement components." (PMID 40843669, 2025). "C5aR1 inhibitors reduce the release of immunosuppressive factors, such as IL-10 and TGF-β, in the tumor microenvironment." (PMID 41373839, 2025). "In contrast, tumor tissues from C5- and C5aR1-deficient mice had increased infiltration of CD8+ T cells compared to wild-type and C3-deficient mice, suggesting that MDSCs may contribute to CD8+ T cell suppression and create an immunosuppressive tumor microenvironment." (PMID 41300283, 2025). "Identification of C5aR1+ on tumor-associated macrophages (TAMs) indicates polarization towards an immunosuppressive phenotype; blocking the C5a/C5aR axis restores TAM anti-tumor responses and activates cytotoxic T cells, alleviating tumor progression." (PMID 40225866, 2025). "In colorectal cancer (CRC), SPP1, C5AR1, MMP3, TIMP1, and ADAM8 were validated as macrophage-related biomarkers influencing tumor progression." (PMID 40422244, 2025). "Changes in the tumor microenvironment also directly increase the phagocytic activity of macrophages selectively toward SCs, and blockade of MEK or blockade of C5AR1 increased phagocytosis of Schwann cells in vitro." (PMID 38458648, 2024). "In particular, one pair of ligands and receptors (C5AR1 and RPS19) was inferred to play key roles in the crosstalk of stroma and tumor regions." (PMID 38729966, 2024). "T127 tumor cells treated in vitro with AZD5305 and then cocultured in a transwell system with C5aR1 macrophages resulted in C5aR1 macrophages that suppressed T cell activation as assessed by positivity for GMZB, PRF1 or IFNγ." (PMID 38802355, 2024). "To directly test whether C5aR1 macrophages from T127 were involved in the transfer of resistance to T22 in the co-transplantation model, we isolated C5aR1hi cells (that are mainly TAM_C3 from the blood of T127 tumor-bearing mice and transferred them to T22 tumor-bearing mice." (PMID 38802355, 2024). "We treated BMD-macrophages from tumor-bearing mice for 1 h ex vivo with MEK inhibitor or vehicle; MEKi significantly increased the intensity of anti-C5aR1/CD88 on tumor macrophage cell surfaces." (PMID 38458648, 2024). "One study reveals that RPS19 expression in tumor cells promotes infiltration of regulatory T cells and reduces infiltration of CD8+ T cells into tumors by interaction with C5AR1 in myeloid-derived suppressor cells." (PMID 38002057, 2023). "C5AR1 and RPS19 were highly expressed in tumor tissue compared with normal tissue in the TCGA-CRC and TCGA-ESCA datasets." (PMID 38002057, 2023). "For example, in TAMs, gene expression of FPR3, PLAUR, and LRP1, the receptor genes interacting with tumor cells, was correlated with ligand genes interacting with CD8+ T cells including C5AR1." (PMID 38002057, 2023). "In the present study, we found that an increase in platelets in the CRC microenvironment promoted tumor growth and metastasis by CD62P binding to PSGL-1 on TAMs, which shifted TAMs toward a protumor phenotype via the C5a/C5aR1 axis." (PMID 37064877, 2023).
tumor (continued). "Autocrine activation of C5aR1 promoted the invasion and migration of HCC cells and was highly correlated with capsular infiltration, tumor stage, and epithelial–mesenchymal transition (EMT)-related indicators." (PMID 36294966, 2022). "Although this group demonstrated C5aR1 expression by EMT6 cells, we found that both C3aR and C5aR1 were undetectable on EMT6 and 4T1 cells at the protein level, suggesting that the anti-tumor effects of EP54 are indirect." (PMID 33430104, 2021). "We explored the relationships between CNAs of the complement component and the tumor immune microenvironment by examining the correlations between CNAs of C3 C5, C3AR1, C5AR1, and dysfunctional T-cell phenotypes in TCGA cancer cohorts." (PMID 34439277, 2021). "Thus, C5aR1 may represent an interesting therapeutic target for many tumour entities." (PMID 33606748, 2021). "Here our findings highlight the significance of WTAP-mediated m6A methylation in C5aR1+ neutrophil-induced tumor glycolysis, suggesting a critical role of WTAP in tumor metabolism." (PMID 34312368, 2021). "Overall, our differential expression analysis suggests tumor context and stage-dependent heterogeneity in the expression of complement components C3, C5, C3AR1, and C5AR1 in different cancer types." (PMID 34439277, 2021). "Specifically, CD55 expression has significant correlation with tumor purity in COAD, and the expression of the complement component C3, complement receptor CR4, and complement activation regulator C5aR1 was statistically related with immune purity in STAD." (PMID 33614473, 2020). "The concept is to block C5aR1, expressed on subsets of MDSC and neutrophils, unleashing thus the anti-tumor activities of the T cells and NK cells." (PMID 33113844, 2020). "C5aR1 and C3aR signal through the PI3K/AKT pathway, and silencing the PI3K or AKT gene in tumor cells reduced impact of C5aR1 and C3aR stimulation on tumor growth." (PMID 33488603, 2020). "For instance, C5aR1 in lung tumor cells activates the p44/42 MAPK and NF-κB signaling pathways leading to the secretion of IL-8, VEGF, and MCP-1 to the tumor milieu." (PMID 31001273, 2019). "Autocrine complement C3 inhibits IL-10-mediated cytotoxic properties of tumor-infiltrating CD8 T lymphocytes through complement receptors C3aR and C5aR1, and enhances melanoma and breast cancer growth." (PMID 31001273, 2019). "C5aR1 expressed on MDSCs is also able to bind ribosomal protein S19 (RPS19), which is released from apoptotic tumor cells into the tumor microenvironment, leading to a shift toward Th2 cell responses with increased levels of immunosuppressive TGF-β." (PMID 31001273, 2019). "Here, we synthesise advances in intracellular and extracellular complement, with emphasis on complement component 3 (C3) and receptors (C3aR1, C5aR1/CD88, C5aR2/C5L2), highlighting how these pathways shape T-cell metabolism, exhaustion programmes and inflammatory tone within tumours." (PMID 41719156, 2026). "Similarly, C5AR1 is markedly upregulated in GBM compared to normal brain tissue, and its activation has been shown to promote cell invasion, migration, and tumor growth, ultimately leading to reduced survival." (PMID 40843669, 2025). "In addition, in the xenograft tumor established with the metastatic UT-SCC-7 cell line, prominent cell surface staining for C5aR1 was also noted in tumor cells in the center of the tumor." (PMID 40056975, 2025). "Among the metastatic RDEBSCC samples, two had moderately positive C5aR1 expression on the cell surface of tumor cells, three showed weak staining, and two were negative." (PMID 40056975, 2025). "C5AR1, a pleiotropic regulator, promoted CRC initiation by fostering a tumor-supportive immune response and might serve as a potential preventive target." (PMID 40864806, 2025).
tumor (continued). "Activation of C5aR1 in the cytoplasm triggers downstream signalling pathways mediated by G protein-coupled receptors, such as the PI3K/AKT and NF-κB pathways, which are thought to enhance tumour cell proliferation, invasion, and metastasis." (PMID 41044172, 2025). ",47, 48, 49 Interestingly, in RDEBSCCs, the expression of C5aR1 on cSCC tumor cells was comparable to that in non-mcSCC, whereas lesser expression was noted in TME fibroblasts." (PMID 40056975, 2025). "Metastatic and non-metastatic primary human cSCCs, premalignant and benign epidermal lesions, and normal skin for C5aR1 were stained with multiplex immunofluorescence and chromogenic immunohistochemistry." (PMID 40056975, 2025). "This pre-treatment approach was intended to model transient, early-phase C5aR1 inhibition and evaluate its impact on the tumor-initiating potential of GBM tumorspheres, independent of systemic pharmacokinetics or host immune responses." (PMID 41353504, 2025). "Using UPR inhibitors and in loss-of-function experiments for transcription factors such as, XBP1, ATF4 and ATF6, we find that C5aR1 expression is complementarily regulated by multiple UPR pathways; highlighting the strong dependence of tumour cells on UPR-dependent C5aR1 signalling." (PMID 40695778, 2025). "Imaging flow cytometry verified an increase in the fluorescence indicating C5aR1 on the tumor macrophage cell surface rather than the numbers of cells expressing C5aR1." (PMID 38458648, 2024). "This pharmacologic blockade did not significantly alter the percentages of C5aR1+ tumor macrophages." (PMID 38458648, 2024). "Neither genetic reduction nor ablation of C5aR1 altered mouse survival, tumor volume, or tumor number." (PMID 38458648, 2024). "C5AR1 knockdown effectively elevated E-cadherin expression and attenuated Vimentin expression in AGS, SGC7901 and MKN28 cells, indicating that aberrantly expressed C5AR1 might be involved in mediating the EMT phenotype of GC cells and even tumor metastasis." (PMID 38425243, 2024). "The results of this study reveal that C5aR1 shapes a non-inflammatory tumor microenvironment in GC and mediates immune evasion." (PMID 36508191, 2023). "Consequently, targeting C5aR1 with a clinical grade and orally active C5aR1 antagonist, PMX205, resulted in improved tumor radiation responses in vivo." (PMID 37824211, 2023). "We, therefore, next asked whether PMX205 could improve response in the AKPT model where we had previously observed robust C5aR1 expression and low CD8+ T cell tumor infiltration." (PMID 37824211, 2023). "The importance of modulating antitumor immune host responses following C5aR1 targeting has been highlighted in previous studies, and ourselves and others have observed reduced tumor burden in C5aR1–/– mice (data not shown)." (PMID 37824211, 2023). "However, in GC tissues with low (+) C5aR1 levels, fewer CD8+ and CD4+ T cells were clustered in the peripheral tumor stroma, and a higher number of immune cells infiltrated the stroma of the tumor parenchyma." (PMID 36508191, 2023). "MDSCs have several chemokine receptors, including CCR1, CCR2, CCR3, CCR5, CCR12, CXCR2, CXCR4, and C5aR1.25In the current study, MDSCs may express CCR1, the receptor of CCL9, which mediated the migration of MDSCs to tumor tissue." (PMID 38046278, 2023). "Together, our data indicate that targeting C5aR1 can improve radiation response even in models with low (or absent) tumor CD8+ T cell infiltration." (PMID 37824211, 2023). "Importantly, a small molecule inhibitor of the C5a receptor (C5aR1), PMX53, enhances infiltration and function of tumor-infiltrating T cells leading to tumor regression in mouse cancer models." (PMID 33936058, 2021). "The aim of the present study was to obtain a broad expression profile of C5aR1 in human non-neoplastic and neoplastic tissues, especially in tumour entities not investigated in this respect so far." (PMID 33606748, 2021).
tumor (continued). "Flow cytometric analysis found no detectable expression of C3aR or C5aR1 protein by either tumor cell line, whereas J774 macrophages and BMDM expressed high levels of both receptors." (PMID 33430104, 2021). "Rather, the colonic CD14+CD163− MNPs display Mo-like morphology, share gene expression with monocytes (FCAR/CD89 and C5AR1/CD88), and are molecularly and functionally distinct from the CD14brightCD163+ Mɸ subset detected in inflamed IBD mucosa, RA synovial fluid, and tumor ascites." (PMID 32230977, 2020). "Another report showed that C5aR1 signaling induced myeloid-derived suppressor cells to produce larger amounts of reactive oxygen species and reactive nitrogen species, which inhibited CD8+ T cell mediated anti-tumor activity, thereby leading to tumor growth." (PMID 33193442, 2020). "This recruitment and activation of MDSC resulted in the reduced infiltration of these organs by CD8+T cells that appears to eliminate metastasizing tumor cells in these sites, as the depletion of CD8+T cells eliminated the beneficial effect of C5aR1 blockade on lung metastatic burden." (PMID 33488603, 2020). "For instance, C5aR1 blockade does not affect tumor angiogenesis in murine models of lung or cervical cancer." (PMID 31001273, 2019). "Accordingly, antagonism to C3aR and C5aR1, but not to a single receptor, suppresses tumor growth and the antitumor effect depends on IL-10 in vivo." (PMID 31379815, 2019). "While this allowed us to isolate tumor-intrinsic effects of C5aR1 inhibition, it may not fully capture therapeutic dynamics achievable through clinical delivery." (PMID 41353504, 2025). "In this study, we found that SUCNR1, C3aR1, C5aR1, MMP14, THBS 1, TSP-1, and TREM2, which are abnormally expressed in tumor tissue in situ, may be potentially associated with lymph node metastasis." (PMID 37744272, 2023). "Targeting C5aR1 does not increase the percentage of CD8+ T cells in the tumor following RT." (PMID 37824211, 2023). "Therefore, our correlation analysis does not support the role of C3, C5, C3AR1, and C5AR1 in regulating tumor infiltration of TAMs and MDSCs and warrants experimental clarification." (PMID 34439277, 2021). "Increased C5ar1 expression also facilitates recruitment of other myeloid cells like neutrophils via IL-1 production and leukotriene B4 (LTB4), while C5a stimulates neutrophil derived tissue factor (TF) synthesis, enhancing tumor growth and metastasis formation." (PMID 33718121, 2020). "Interestingly, C5a stimulation of human endothelial cells led to increased expression of VEGF165 isoform and C5aR1 blockade by PMX53 attenuated tube formation mediated by VEGF, suggesting that the interplay between C5aR1 and VEGF plays a role in complement-dependent regulation of tumor angiogenesis." (PMID 33271774, 2020). "Although the growth of squamous cell carcinoma in mice was not significantly affected by either paclitaxel or C5aR1 antagonist PMX-53 monotherapy, the combination of both treatments was synergistically effective in reducing tumour growth rate." (PMID 39765018, 2025). "MEK inhibition recruited C5AR1 to the macrophage surface; short-term inhibition of C5aR elevated macrophage apoptosis and Schwann cell death, without affecting MEK-induced tumor shrinkage." (PMID 38458648, 2024). "In particular, C3aR1, C5aR1, MMP-14, THBS1, and TREM2 were abnormally highly expressed in orthotopic tumor tissue but were not expressed in lymph node metastasis-negative tissues." (PMID 37744272, 2023). "We selected C5AR1, CLEC4A and NLRP3 based on their significant protein expression in tumor-infiltrating lymphocytes, but not in normal lymphoid tissue." (PMID 36323738, 2022). "While the lack of C3aR or C5aR1 expression by EMT6 and 4T1 tumor cells precludes direct effects of complement proteins on tumor growth, direct effects are possible for other (receptor-expressing) tumor models." (PMID 33430104, 2021).
tumor (continued). "To examine the influence of C5aR1+ neutrophils on BC cells, we co-cultured C5RN with two cell lines, MCF-7 and MDA-MB-231 (tumor cells: neutrophils, 10:1), by using a non-contacting transwell system." (PMID 34312368, 2021). "In addition, C5aR1 showed a negative correlation with NK cells, CD8+ T cells, and dendritic cells, and the infiltration level of tumor-infiltrating immune cells was significantly reduced." (PMID 36508191, 2023). "C5aR1 showed a negative correlation with the immunological status of TME and a positive correlation with most immune checkpoints in GC, including PD-L1, CTLA-4, LAG-3, and PD-1, which suppress the effector function of T cells and impede anti-tumor immunity." (PMID 36508191, 2023). "Three significant up-regulated genes which had the presence of antibody-specific, immunohistochemistry-based protein expression on tumor-infiltrating lymphocytes (TILs) in tumor specimen, but not in normal lymphoid tissue, were selected including CLEC4A, C5AR1, NLRP3." (PMID 36323738, 2022).